ERG (ETS transcription factor ERG)
Diseases named in the same sentence as ERG in open-access papers (continued):
Sharing a sentence is not in itself a finding about the gene and the disease.
prostate carcinoma (continued). "The HNRNP2AB1 promoter is fused to ETS factors in some prostate cancer patients and this promoter results in lower, more physiological ERG expression than CMV promoter constructs, but can still drive cell migration and tumor growth." (PMID 33554122, 2021). "Topics enriched in Samples 4 and 16 include genes such as AR, GRHL2, FOXA1, SLC43A1, WNT7B, which are known downstream players active in prostate cancers with ERG expression." (PMID 34911933, 2021). "In another report, it was found that 17% of prostate cancer cases with multifocal tumors showed both ERG and SPINK1 overexpression within different regions of either the same tumor focus or different foci, but not in the same tumor cells." (PMID 33634124, 2021). "ERG is an ETS-family transcription factor that is frequently upregulated in prostate cancer as a result of a translocation involving the TMPRSS2 gene." (PMID 34884985, 2021). "FZD8 is a downstream target of multiple oncogenes including ETS-related gene (ERG) in prostate cancer, SRC in lung adenocarcinoma, and Mesenchymal–Epithelial Transition (MET) in HNSCC." (PMID 34604862, 2021). "More recently, combined detection of urinary prostate cancer gene 3 (PCA3) and TMPRSS2:ERG has been shown to improve the sensitivity for prostate cancer diagnosis." (PMID 33634124, 2021). "In contrast, we show here that mutually exclusive prostate cancer driver alterations involving the ERG transcription factor and the ubiquitin ligase adaptor SPOP are synthetic sick." (PMID 33531470, 2021). "This study sheds light on the molecular mechanisms of PI3K/AKT and RAS/ERK regulation of ERG function in prostate cancer." (PMID 34314419, 2021). "Later, ERG/SPINK1 immunohistochemistry analyses performed in different foci of prostate cancer samples revealed that ERG and SPINK1 overexpression were mutually exclusive in all tumor foci." (PMID 33634124, 2021). "Recurrent gene rearrangements involving the androgen-regulated transmembrane protease serine 2 (TMPRSS2) and ETS transcription factor, v-ets erythroblastosis virus E26 oncogene homolog (ERG) occur in ~50% of prostate cancer (PCa) patients." (PMID 34493733, 2021). "About 50% of prostate cancer (PCa) tumors are TMPRSS2:ERG (T2E) fusion-positive (T2E+), but the role of T2E in PCa progression is not fully understood." (PMID 33669024, 2021). "The target proteins of E3 ligases in prostate cancer, among others, are the driving proteins, such as AR, ERG, PTEN, cell-cycle progression proteins, and other transcription factors and signaling molecules." (PMID 33572160, 2021). "In the future, the role of ERG-mediated splicing regulation deserves to be investigated, in these cells as well as in additional context where these proteins are involved (e.g. prostate cancer cells)." (PMID 34009296, 2021). "Markers selected for the model include well-known genes associated with prostate cancer and proven in other diagnostic tests, such as PCA3, HOXC6, and the TMPRSS2/ERG gene fusion." (PMID 33925381, 2021). "They showed that the TMPRSS2:ERG positive VCaP prostate cancer cells overexpressed the fusion product when treated with synthetic androgens." (PMID 33634124, 2021). "In prostate cancer, it is important to analyze IL-6 signaling in the context of coexpression with ERG." (PMID 34204596, 2021). "Chromosomal deletions represent the second most frequent type of recurrent genomic aberrations in prostate cancer after TMPRSS2:ERG fusions." (PMID 32417965, 2020). "The SE-associated lineage-specific machinery of ERG is linked with the TFs like FOXA1 and HOXB13, which play important roles in prostate-cancer-specific gene expression." (PMID 33299103, 2020). "Mechanistically, we showed that endothelial cells-derived FGF2 mediated ERG expression and Akt/mTOR activation in prostate cancer cells." (PMID 33425737, 2020). "The ERG oncogene, a member of the ETS family of transcription factor encoding genes, is a genetic driver of prostate cancer." (PMID 32581342, 2020).
prostate carcinoma (continued). "About 50% of all prostate cancers carry a gene fusion linking the androgen‐regulated serine protease TMPRSS2 with the ETS‐transcription factor ERG resulting in an androgen‐related overexpression of ERG." (PMID 31736271, 2020). "Collectively, these findings suggested that ERG enhances docetaxel resistance via the Akt/mTOR signaling pathway in prostate cancer cells." (PMID 33425737, 2020). "Mouse prostate organoids were modified to carry the TMPRSS2-ERG fusion, a genetic alteration present in more than 50% of prostate cancers that leads to high ERG expression driven from the androgen-responsive promoter of the TMPRSS2 gene." (PMID 32019175, 2020). "We also tested their effect on xenograft tumour growth in mice and on ERG protein expression in a human prostate cancer radical prostatectomy sample ex vivo." (PMID 32581342, 2020). "Although ERG overexpression lacks prognostic relevance in prostate cancer, it modulates the expression of more than 1600 genes in prostate epithelial cells." (PMID 32417965, 2020). "Collectively, these data suggested that endothelial cells enhance the docetaxel resistance of prostate cancer cells through increasing ERG expression." (PMID 33425737, 2020). "About 50% of prostate cancers contain gene fusions connecting the androgen-regulated TMPRSS2 gene with the transcription factor ERG." (PMID 32377272, 2020). "TMPRSS2:ERG fusions are observed in about 50% of prostate cancer resulting in permanent overexpression of the transcription factor ERG." (PMID 32677026, 2020). "We tested their efficacy in terms of inducing exon 4 skipping in two ERG-positive cell lines, VCaP prostate cancer cells and MG63 osteosarcoma cells." (PMID 32581342, 2020). "As for ERG, it synergistically regulates by physically interacting with prostate-cancer-specific regulators AR, HOXB13, and FOXA1." (PMID 33299103, 2020). "Other common prostate cancer associated genes such as TMPRSS2 and ERG show similar expression patterns." (PMID 33303959, 2020). "ERG protein activates Akt/mTOR signaling pathway contributing to docetaxel resistance in prostate cancer cells ultimately." (PMID 33425737, 2020). "TMPRSS2:ERG fusions occur in almost half of all prostate cancers and induce overexpression of the transcription factor ERG." (PMID 33195694, 2020). "To test if the lead compounds alter protein stability or transactivation function, we used the VCaP prostate cancer cell line which harbors the TMPRSS2/ERG rearrangement." (PMID 32915889, 2020). "We showed that endothelial cells-derived FGF2 can induce ERG expression in prostate cancer cells in an AR-independent manner." (PMID 33425737, 2020). "Gene rearrangements in SLC45A3 were concurrent with ERG rearrangements in a prostate cancer cohort, with SLC45A3-ERG gene re-arrangement associated with loss of SLC45A3 protein expression and an unfavorable clinical course in prostate cancers." (PMID 32584883, 2020). "Aberrant expression of the transcription factor ERG is a key driving event in approximately one-half of all of prostate cancers." (PMID 32915889, 2020). "The TMPRSS2:ERG fusion, which occurs in 40–50% of prostate cancer patients and results in ERG expression, is an early genomic event during tumor development." (PMID 32054861, 2020). "Overall, these findings demonstrated a synergistic role of endothelial cells in contributing to prostate cancer proliferation and chemoresistance via inducing ERG expression and activating the Akt/mTOR signaling pathway." (PMID 33425737, 2020). "Further, a combination of TBX15 and other hypermethylated genes is a useful biomarker for ERG expression and recurrence of prostate cancer." (PMID 33447348, 2020). "For example, TBX15 is a methylation marker of prostate cancer associated with advanced stage and ETS-related gene (ERG) expression, which regulates cell proliferation, angiogenesis, and apoptosis." (PMID 33447348, 2020).
prostate carcinoma (continued). "A recurrent fusion gene in prostate cancers, ERG (erythroblast transformation-specific related gene), was shown to interact and collaborate with AR through chromatin looping." (PMID 32634370, 2020). "We specifically chose to target the interaction between ERG and EWS, since ERG is the most commonly rearranged ETS factor in prostate cancer." (PMID 32915889, 2020). "Endothelial cells secrete FGF2 in the tumor microenvironment to enhance the expression of ERG in prostate cancer cells." (PMID 33425737, 2020). "To determine which factor contributes to the expression of ERG in prostate cancer cells co-cultured with HUVEC, we conducted cytokines array according to the manufacturer’s protocol." (PMID 33425737, 2020). "This is the first study aimed at targeting the ERG-EWS protein-protein interaction for the development of a small molecule-based prostate cancer therapy." (PMID 32915889, 2020). "The presence of the TMPRSS2:ERG fusion was demonstrated by next-generation sequencing on both malignancies, leading to the assumption that the lung nodule was a metastasis from the prostate cancer." (PMID 33419298, 2020). "A common alteration in prostate cancer is gene fusion, and specifically fusion between androgen-regulated promoters with ERG or other ETS transcription factors genes." (PMID 32365491, 2020). "One other example of the clinical relevance of AR and ERG chromatin loops is the link detected between a prostate cancer GWAS SNP, rs9364554, located in the intron of SLC22A3 within an AR and ERG loop anchor." (PMID 32634370, 2020). "Previously this fusion had been modelled by artificial ERG overexpression and studied in human prostate cancer cell lines and mouse models, but this approach for the first time allows investigation of its effect in a wildtype background." (PMID 32019175, 2020). "During gene fusion, the 5′-untranslated region of TMPRSS2 is merged with the transcription factors, ERG or ETV genes which enhance prostate cancer progression and invasion." (PMID 32764454, 2020). "Next, we examined the effect of IL-6, IL-8, CCL5, and FGF2 in the regulation of ERG expression by adding them to the culture media of prostate cancer cells, respectively." (PMID 33425737, 2020). "For instance, PCAT5 is a long noncoding RNA regulated by the ERG, an active transcription factor common in human prostate cancer." (PMID 33033484, 2020). "Our recent study also shows that ERRα and ERG can synergistically regulate each other at the transcriptional level and both form a reciprocal regulatory loop to promote the advanced growth of prostate cancer." (PMID 32226548, 2020). "Only one report suggested that the expression of LOC284930 was positively correlated with ERG overexpression, which is the most frequent genomic rearrangement in prostate cancer." (PMID 33179733, 2020). "Specifically, we demonstrated that FGF2 secreted from endothelial cells can upregulate ERG expression in prostate cancer, which then activates the Akt/mTOR signaling pathway and promote docetaxel resistance of prostate cancer subsequently." (PMID 33425737, 2020). "Expression of a point mutant of ERG that disrupts the interaction with EWS results in a significant decrease in prostate cancer cell migration, clonogenic growth, and anchorage independent growth as well as decreased tumor formation in mice." (PMID 32915889, 2020). "As a prostate-specific gene, TMPRSS2 fuses with the transcription factor ERG gene in a large proportion of human prostate cancers and plays an important role in selected pathological processes." (PMID 33193689, 2020). "The related kallikrein gene KLK2 had expression that was highly correlated with KLK3, as did TMPRSS2, one of the genes involved in the TMPRSS2:ERG translocation that is common in prostate cancer." (PMID 33303959, 2020). "The TMPRSS2:ERG fusion status of the prostate cancers on the TMA has been determined previously by FISH and IHC." (PMID 33339518, 2020).
prostate carcinoma (continued). "TMPRSS2:ERG fusions affect about 50% of prostate cancers and lead to a constitutive overexpression of the transcription factor ERG." (PMID 32143573, 2020). "Here, we included data on the TMPRSS2:ERG fusion (occurring in about 50% of prostate cancers), the most common recurrent chromosomal deletions (3p, 5q, 6q, 8p, 10q/PTEN, 12p, 12q, 13q, 16q, 17p, 18q), and the Ki67LI as well as AR protein expression levels." (PMID 32417965, 2020). "Herein, docetaxel resistance of ERG-overexpressing prostate cancer cells was significantly reversed when Perifosine, the inhibitor of the Akt/mTOR signaling pathway was added, which was in agreement with the previous report." (PMID 33425737, 2020). "The use case in this section highlights some of the strengths of each individual tool and also demonstrates how the tools can be used synergistically to gain a fuller understanding of a genomic event, in this case ERG fusions in prostate cancer." (PMID 32636365, 2020). "Recent studies have revealed that ERG can promote resistance to docetaxel in different prostate cancer cell lines." (PMID 33425737, 2020). "There is a strong correlation between BRACHYURY expression and well-established markers of prostate cancer progression, such as Bcl2, ETS-related gene (ERG), and phosphatase and tensin homolog (PTEN) loss." (PMID 32695672, 2020). "The combination of rucaparib with radiation therapy was synergistic for prostate cancer cells expressing the TMPRSS2:ERG gene fusion, as these cells showed enhanced sensitivity towards rucaparib, which increased radiation response." (PMID 33233320, 2020). "Gene fusion between TMPRSS2 and members of the E26 transformation specific (ETS) transcription factor family (ERG or ETV) is another mechanism by which TMPRSS2 plays a role in prostate cancer progression." (PMID 32764454, 2020). "Comparing RWPE-1 data with those of the TMPRSS2-ERG fusion-positive VCaP prostate cancer cells provides even information about those genes which have become under the control of the mis-expressed ERG in the cancer cells." (PMID 31818883, 2020). "Prostate cancer patients usually carry the TMPRSS2/ERG (T/E) fusion gene, and T/E can activate the NF-κB pathway through phosphorylation of NF-κB p65 Ser536 (p536) to promote the occurrence and development of prostate cancer." (PMID 33061854, 2020). "Conversely, a gradual decrease of SOX9 has been related to a progression to advanced stage, high Gleason grade, and metastatic growth in ERG-positive cancers, and these effects were strictly limited to the subset of prostate cancers harboring PTEN deletions." (PMID 31057614, 2019). "Exosomes from urine possess mRNA-encoding protein prostate cancer-associated 3 (PCA3) and the transmembrane protease serine 2 (TMPRSS2)–erythroblast transformation-specific (ETS)-related gene (ERG) fusion product, an entity over-expressed in prostate cancer." (PMID 30699987, 2019). "A recent comprehensive study of chromatin modification and transcription factor binding allowed to classify primary prostate cancer with ETS-related gene (ERG) translocation into clusters characterized by high or low ERG expression or by a NEPC-like profile." (PMID 31200487, 2019). "Our previous study demonstrated that ERG factor regulates the expression of these enzymes in prostate cancer cells." (PMID 31638934, 2019). "As mentioned in the section on genetic abnormalities, the fusion of the AR-regulated TMPRSS2 gene with ERG is a very frequent event during early stages of prostate cancer tumorigenesis." (PMID 31366128, 2019). "About 50% of prostate cancers carry gene fusions linking the androgen-regulated TMPRSS2 with the transcription factor ERG." (PMID 30823906, 2019). "The oncogenic activation of ERG by these gene fusions is detected in 50% to 65% of prostate cancer patients of European ancestry." (PMID 31013716, 2019).
prostate carcinoma (continued). "Intra-chromosomal translocation of the transmembrane protease serine 2 (TMPRSS2) gene to the ETS family member ERG is the most prevalent fusion in prostate cancer and the fusion gene is expressed in the VCaP cell line." (PMID 30664691, 2019). "The protein expression profile included ERG, AMACR (prostate cancer associated), and Prostein (prostate epithelium specific) of cells captured from the post-DRE urine specimens." (PMID 31013716, 2019). "The HDAC inhibitors can indeed reduce cancer growth by inducing apoptosis of ERG positive prostate cancer cells." (PMID 31817884, 2019). "TMPRSS2-ERG is the frequent ERG gene rearrangement observed in prostate cancer and SLC45A3 is the second most common ERG partner in prostate cancer and in most of patients SLC45A3-ERG rearrangements co-occur with TMPRSS2-ERG rearrangements." (PMID 31366128, 2019). "TRIM25 as an ubiquitin ligase, targets ERG, mediating ERG polyubiquitination and stabilization in prostate cancer." (PMID 31137886, 2019). "ERG mRNA expression level, evaluated by NanoString, qRT-PCR, and IHC, was identified as an independent predictor of prostate cancer progression." (PMID 31741711, 2019). "In primary tumors, ERG is frequently overexpressed in prostate cancer due to genomic fusions, placing ERG under the control of AR regulated promoters." (PMID 31798767, 2019). "This is lineage-specific since oncogenic ERG in prostate cancer VCaP cells binds different super-enhancers compared with human umbilical vein endothelial cell." (PMID 30892142, 2019). "The recurrent fusions between the androgen-regulated TMPRSS2 and ETS transcription factor genes (primarily ERG) occur in about 50% of primary prostate cancers." (PMID 31404966, 2019). "The Expression Status of ERG in prostate cancer has been extensively studies in prostate cancer specimens." (PMID 30658688, 2019). "The genomic rearrangements leading to the fusion of the AR-regulated TMPRSS2 gene promoter and the N-terminally deleted ERG coding sequence represents the most common prostate cancer-specific driver gene alteration." (PMID 31013716, 2019). "Depletion of USP11 enhanced growth, invasion, and glucose and glutamine metabolism in ERG-negative 22Rv1 human prostate cancer cells stably overexpressing ERG (22Rv1ERG)." (PMID 30733438, 2019). "We have recently shown that ERG regulates intra-tumoral androgen synthesis and thereby facilitates AR function in prostate cancer cells." (PMID 31638934, 2019). "TMPRSS2:ERG fusions occur in about 50% of prostate cancers and result in a permanent expression of the transcription factor ERG." (PMID 31606028, 2019). "This activity has been shown to sensitize prostate cancer cells to androgen deprivation and to synergistically inhibit proliferation, in particular in ERG-positive prostate cancer." (PMID 30841549, 2019). "Oncogenic activation of ERG represents an early prostate cancer driver event and is, therefore, an appropriate therapeutic target to attempt an early eradication of this neoplasia." (PMID 31366128, 2019). "Similar spatial proximity during interphase has been proposed to mediate RET and H4 fusion in papillary thyroid carcinoma, and TMPRSS2 and ERG in prostate cancer." (PMID 31007851, 2019). "In prostate organoid models, BAF complexes are required for ERG-mediated basal-to-luminal transition, a typical feature of ERG activity in prostate cancer." (PMID 31366128, 2019). "T/E fusion results in constitutive expression of ERG oncoprotein resulting in enhanced proliferation and invasive potential of prostatic cancer cells." (PMID 30658688, 2019). "Preclinical studies showed that PARP1 can interact with ERG, and inhibition of PARP1 enhanced DNA double-strand breaks induced by ERG overexpression and slowed the growth of ERG-positive prostate cancer cells." (PMID 31404966, 2019).